CD4 (CD4 molecule)
Diseases named in the same sentence as CD4 in open-access papers (continued):
Sharing a sentence is not in itself a finding about the gene and the disease.
tuberculosis (continued). "Opportunistic infections (OI), tuberculosis (TB), CD4 cells <50/μl, and viral load >5 log10 copies/ml increased the odds of treatment failure both at 6 and 12 months." (PMID 29995957, 2018). "BCG-mediated protection against TB relies on mounting superior Mycobacterium tuberculosis (Mtb)-specific CD4+ and CD8+ T cell responses." (PMID 29848490, 2018). "Thus, a combined cell surface loss of expression of CD45RA, CCR7, and CD127 on M. tuberculosis–specific CD4+ T cells is associated with both tuberculosis and recently acquired LTBI but not with remotely acquired LTBI." (PMID 28329119, 2017). "To date, tuberculosis (TB) vaccine candidates have been designed predominantly to stimulate a T helper 1-type CD4 T-cell response, and as a natural consequence Elispot has been used in most of them in order to access the specific cellular response." (PMID 28961208, 2017). "It is generally thought that Mycobacterium tuberculosis (Mtb)-specific CD4+ Th1 cells producing IFN-γ are essential for protection against tuberculosis (TB)." (PMID 28871253, 2017). "The demonstration of the capacity of HBHA to induce IL-17 synthesis by CD4+ T lymphocytes in the very young M. tuberculosis-infected children, therefore, points toward a new protective mechanism against TB disease when IFN-γ production is suboptimal." (PMID 28928738, 2017). "However, little is known about CD8, as compared to CD4, antigens in tuberculosis." (PMID 28775896, 2017). "It is generally assumed that host protection against TB relies on IFN-γ-producing CD4+ T cells that are able to activate macrophages for Mycobacterium tuberculosis (Mtb) killing." (PMID 28871253, 2017). "These factors included linkages to ART, the CD4 count levels, the presence of other diseases like tuberculosis (TB), and duration of exposure to the intervention." (PMID 27253974, 2016). "CD4 T cells and granulocytes produce IL-22; however, the effector CD4 T cells from TB patients only increase IL-22 production when stimulated with M. tuberculosis proteins in vitro." (PMID 27375607, 2016). "Most work has reported the effect of HIV on TB immune response during active TB; and fewer studies have compared the attributes of mycobacterial-specific CD4+ T cells in the context of latent tuberculosis infection in HIV-uninfected and HIV-infected persons." (PMID 27865393, 2016). "Taken together, our results demonstrated that MTB-specific IL-21+IFN-γ+CD4+ T cells from local sites of tuberculosis (TB) infection could be enhanced by IL-12, which have the features of both Tfh and Th1 cells and may have an important role in local immune responses against TB infection." (PMID 26785168, 2016). "Little is known about the expression of inhibitory molecules cytotoxic T-lymphocyte antigen-4 (CTLA-4) and programmed-death-1 (PD-1) on Mycobacterium tuberculosis (Mtb)-specific CD4 T-cells and how their expression is impacted by TB treatment." (PMID 27367521, 2016). "This is complicated by the fact that patients may be eligible to switch for more than 1 event within overlapping intervals; so, for example, a patient whose CD4 count drops below 100 may become eligible to switch but then receive a tuberculosis diagnosis within the grace period prior to switching." (PMID 26316598, 2015). "In addition to the roles of CD4+ T cells in immune protection against tuberculosis in humans, M. tuberculosis antigen-specific CD4+ T cells may contribute to immunopathology in the lungs and other organs." (PMID 26018190, 2015). "Consistent risk factors for early mortality include low CD4 count, advanced WHO disease stage, the presence of opportunistic infections such as tuberculosis (TB), and malnutrition, usually indicated by low body mass index (BMI)." (PMID 25630368, 2015).
tuberculosis (continued). "Empirical treatment for TB was more frequent in PLHIV with low CD4 counts, anemia, history of opportunistic infections, weight loss, previous tuberculosis, negative bacteriology test (as opposed to not having a test) and abnormal chest X-ray." (PMID 24679187, 2014). "At BMC, even though most HIV-positive hospitalized patients at BMC may qualify to begin ART either based on CD4 counts (mean CD4 count of 248 cells/mm3) or presence of an opportunistic infections like tuberculosis, still <1% of HIV positive patients are initiated on ART in the wards." (PMID 25465206, 2014). "M. tuberculosis-specific CD8+ T cells have been found to be present in granulomas and pleural exudates of TB patients sometimes more in numbers than that of CD4+ T cells." (PMID 25356553, 2014). "The experience from the Jagori Ward's first 21 months (from May 2008 to February 2010) has been previously reported; we found that 38% of those who died had active tuberculosis (TB) and that the majority of patients admitted to the ward had a CD4 cell count <50 cells/mm3." (PMID 25485634, 2014). "Here we show that Isoniazid (INH) treatment dramatically reduces Mycobacterium tuberculosis antigen-specific immune responses, induces apoptosis in activated CD4+ T cells, and renders treated animals vulnerable to TB reactivation and reinfection." (PMID 25202011, 2014). "Given that advanced HIV is associated with increased risk of development of tuberculosis, it is interesting to observe that the median CD4 count was higher among those who were positive for TB compared to those who were non-TB among our HIV positive group." (PMID 25340424, 2014). "As for the seven essential services, survey respondents reported that CD4+ cell count testing was available to all but one site, while tuberculosis (TB) screening and community outreach services were available in 80 and 72%, respectively." (PMID 25516092, 2014). "Since we did not measure CD4 counts or test for tuberculosis and other underlying conditions, we could not evaluate the influence of these parameters on the occurrence of bacteraemia." (PMID 25526763, 2014). "On the other hand, current studies have shown that the risk M. tuberculosis/HIV co-infection is higher among people who are immunosuppressed or live in close contact with people who have active TB or have a CD4 cell count below 200 cells/mm3." (PMID 25358465, 2014). "Taken together, these results indicate that active TB patients have significantly elevated expression of CD244/2B4 on M. tuberculosis antigen-responsive CD4+ T cells." (PMID 23638187, 2013). "Higher prevalence of tuberculosis (n = 21/71, 29.58%), diarrhea (n = 4/71, 5.63%), oral candidiasis (n = 16/71, 22.53%), skin fungal infections (n = 4/71, 5.63%), pneumonia (n = 3/71, 4.22%) and others (n = 4/71, 5.63%) were found in patients with CD4 count less than 200/mm3." (PMID 24330921, 2013). "In summary, our study demonstrated that CD244/2B4 expression on M. tuberculosis antigen-responsive CD4+ T cells was significantly higher in active TB patients than in latent TB infection individuals." (PMID 23638187, 2013). "Patients who initiated ART >60 or >90 days after TB diagnosis had delayed progression from tuberculosis to death after adjusting for CD4+ lymphocyte count." (PMID 24066096, 2013). "A recent systematic review and meta-analysis of the impact of HAART on incidence of tuberculosis in PLHIV in developing countries show a reduction in TB incidence across all baseline CD4 counts." (PMID 23675515, 2013). "Active TB patients had significantly elevated CD244/2B4 expression on M. tuberculosis antigen-specific CD4+ T cells compared with latent infection individuals." (PMID 23638187, 2013). "Therefore, CFP10 may be a candidate for inclusion in a tuberculosis vaccine designed to elicit both CD4+ and CD8+ T cell response." (PMID 24349220, 2013).
tuberculosis (continued). "Therefore, network-regulated apoptosis is important for the fate of CD4+ T cells and might indirectly affect tuberculosis outcome." (PMID 22719887, 2012). "In addition to their roles in providing protective immunity against tuberculosis, M. tuberculosis antigen-specific CD4 T cells may also contribute to immunopathology in the lungs and other organs." (PMID 22880090, 2012). "Stool microscopy, HIV serology, serum IgE level, eosinophil and CD4 counts were performed and tuberculosis patients were followed up for 3 months after initiation of anti-TB treatment." (PMID 22952620, 2012). "This is, for example, a well-recognized concern with conventional sputum smear microscopy for tuberculosis (TB), and laboratory-based CD4 and viral load testing for HIV." (PMID 22973183, 2012). "In particular, the number of peripheral blood CD4 T cells at the time of TB diagnosis in HIV-TB coinfected individuals correlates closely with the likelihood that a patient will have cavitary tuberculosis." (PMID 22880090, 2012). "M. tuberculosis antigen-specific CD27− CD4+ memory T lymphocytes have been proposed as a quick blood-based tool to diagnose active TB." (PMID 22778764, 2012). "For example, multiple studies have revealed that, in HIV-infected patients with active tuberculosis, the frequency of cavitary lung lesions is directly proportional to the number of the number of peripheral blood CD4 T cells at the time of TB diagnosis." (PMID 22880090, 2012). "Newly discovered IL-9–producing CD4+ helper T cells (Th9 cells) have been reported to contribute to tissue inflammation and immune responses, however, differentiation and immune regulation of Th9 cells in tuberculosis remain unknown." (PMID 22363712, 2012). "CD4+ CD45RO+ T cells co-expressing granulysin with specificity for Mycobacterium tuberculosis (Mtb) were present in high frequency in TB-experienced children and adolescents." (PMID 22216262, 2011). "Protection from tuberculosis (TB) relies on both CD4+ and CD8+ T cells with the former described as the most important." (PMID 34603628, 2011). "Interestingly, patients with active tuberculosis had higher frequencies of PPD reactive cytokine-positive CD4 T cells (median 0.81%, interquartile range (IQR) from 0.35–1.73%) than individuals with successfully treated disease (median 0.39%, IQR 0.10–0.73%, p = 0.02, Mann-Whitney test)." (PMID 21423578, 2011). "There is a synergistic relationship between tuberculosis and HIV infection: each accelerates the progression of the other; and HIV-seropositive subjects with TB have a shorter life than TB-free HIV-seropositive subjects with comparable CD4+ T cell counts." (PMID 21209722, 2010). "For this reason, it is argued that in TB-HIV co-endemic countries, AIDS patients usually die of tuberculosis or other infections before their CD4+ count falls low enough for NTM to cause a disease." (PMID 20436962, 2010). "HIV-infected individuals with latent Mycobacterium tuberculosis (Mtb) infection are at significantly greater risk of reactivation tuberculosis (TB) than HIV-negative individuals with latent TB, even while CD4 T cell numbers are well preserved." (PMID 20224771, 2010). "TB-IRIS is more likely to occur in patients with a low baseline CD4 count, a short duration between initiation of antitubercular treatment and cART and disseminated tuberculosis." (PMID 19229341, 2009). "Both of the participants who died of suspected TB had CD4 counts of <100 cells/mm3 at the time of screening, one woman had been treated for tuberculosis for 4 mo prior to her death." (PMID 19859531, 2009). "For this reason, enhanced performances in a higher proportion of tuberculosis identified infected subjects in the lower CD4+ cell count group was observed for T-SPOT-TB as compared to QF-TB-G or QF-TB-IT." (PMID 19343092, 2008).
tuberculosis (continued). "Hubo 33,3 % de mortalidad intrahospitalaria, asociada con el número de linfocitos T CD4+ (p < 0,05), el diagnóstico de novo de HIV (p < 0,04) y la presencia de tuberculosis meníngea (p < 0,03)." (PMID 40865109, 2025). "In patients with active tuberculosis (ATB), an increased frequency of CD4+ T cells has been observed, while CD8+ T cells display a reduced frequency and exhibit an exhausted phenotype characterized by the expression of CD39, CD279, and TIM-3." (PMID 40825006, 2025). "In outpatients, tuberculosis LAM screening is recommended in those who have tuberculosis symptoms, are seriously ill or at CD4 below 100 cells/μL." (PMID 39046150, 2025). "Mycobacterium tuberculosis may cause more TB in all stages of HIV infection than in the general population, with the incidence of TB and the spread of pulmonary TB to other organs increasing as the CD4 count decreases." (PMID 40748951, 2025). "Our findings reaffirm the impact of gender, anaemia, hypertension, tuberculosis, advanced HIV disease (WHO clinical stages 3 and 4, low CD4 counts) and high viral load on weight changes in the study population." (PMID 40433484, 2025). "Th1 cells also dominate the Mtb-specific CD4+ T cell response in C57BL/6 mice, the most widely used animal model of tuberculosis." (PMID 40489538, 2025). "Current guidelines recommend tuberculosis lipoarabinomannan (LAM) reflex testing in inpatients who either have tuberculosis symptoms, who have AHD or are seriously ill, or who have CD4 below 200 cells/μL." (PMID 39046150, 2025). "Urinary lipoarabinomannan levels are known to be elevated in individuals with tuberculosis-HIV coinfection and to increase with decreasing CD4 cell counts." (PMID 41172414, 2025). "Although TB is also severe in people with HIV (PWH), M. tuberculosis (MTB) exhibits higher pathogenicity and can cause active disease in PWH with relatively higher CD4+ T cell counts (albeit still indicative of immunosuppression)." (PMID 40936199, 2025). "Participants had a median increase (95% CI) in CD4 count of 192 cells/μL since TLD initiation, and the cumulative incidence of tuberculosis was 3/127 (2%)." (PMID 40356938, 2025). "The predictive value of the QFT+ test for identifying individuals who would develop active tuberculosis appeared limited in this setting, with the possible exception of PLHIV who had ongoing viral replication and low CD4 counts." (PMID 40823191, 2025). "Among PLHIV with detectable HIV-load, the incidence was higher in persons with low CD4 T-cell counts, positive QFT+ tests, or in persons originating from high tuberculosis incidence countries." (PMID 40823191, 2025). "Robust CD8+ T-cell responses, supported by Th1-biased CD4+ immunity, are increasingly recognized as central for vaccines against HIV, tuberculosis, malaria, CMV, and emerging zoonoses." (PMID 41341596, 2025). "In contrast, in patients with tuberculosis, a double expression of IFN-γ and IL-17 by CD4+ T cells was correlated with the severity of the disease." (PMID 38410517, 2024). "Deaths from tuberculosis were similar across both sexes, and most (n = 5, 71%) were classified as WHO stage 3 or stage 4, with varied baseline CD4 and mostly ambulatory functional status (n = 5, 71.43%)." (PMID 39507464, 2024). "Significant variables with p-value < 0.2 from the bivariate analysis were site, regimen, viral load, baseline CD4 count, gender, WHO stage, and tuberculosis, which were used to perform the multivariate analysis." (PMID 39058196, 2024). "Comparing humans and animal models with TB, there is a significant overlap in DNA hypermethylation changes in CD4+ and CD8+ T cells, demonstrating the role of M. tuberculosis in epigenetic modifications in genes related to immune system cells that decrease their function over time." (PMID 38903242, 2024).
tuberculosis (continued). "Comparing Malakal (n = 400) and Bissau (n = 133) cohorts, patients from Bissau were older, had more history of tuberculosis contact, and presented with more HIV infection and lower CD4 cell counts." (PMID 38798893, 2024). "To assess the impact of Kyn on CD4+ and CD8+ T-cell function, we divided tuberculosis patients into high- and low-Kyn-expressing groups." (PMID 39438693, 2024). "Comparing patients with tuberculosis with unlikely tuberculosis patients, those with tuberculosis presented with a similar proportion of SAM, but those with tuberculosis had more HIV infection and lower CD4 cell counts and more exposure to tuberculosis." (PMID 38798893, 2024). "Additionally, the significant reduction in CD4+ T lymphocytes in TB-COPD patients indicates that the immune function of patients with coexisting COPD and tuberculosis is more severely impaired." (PMID 39432654, 2024). "Individuals with low CD4 counts have an increased likelihood of contracting or re-activating a wide range of opportunistic infections (OIs) including histoplasmosis, cryptococcosis, and tuberculosis (TB)." (PMID 39452647, 2024). "In our report, although the patient was HIV-negative and had no history of immunosuppressive agents or biologic agents, the CD4 + cell count exhibited a significant decrease, indicating severe immunosuppression; this could be the primary factor contributing to the dissemination of tuberculosis." (PMID 38515054, 2024). "Three high HIV burden countries in Africa (Malawi, Zambia and Uganda) have already issued national guidelines recommending ART within or at two weeks after starting tuberculosis treatment for people with tuberculosis and HIV at all CD4 cell counts." (PMID 38675837, 2024). "BCG, the currently used tuberculosis vaccine, induces significant levels of IFN-γ-expressing CD4+ T cells when administered intradermally." (PMID 38400112, 2024). "In the DS tuberculosis model, double immunization with TB/FLU-06E at the start of the HR therapy resulted in a significantly higher level of total spleen-derived cytokine-producing CD4+ and CD8+ Tem cells (CD44+ CD62L-), with a markedly higher proportion of IFN-γ and IFN-γ,TNF-α producing cells." (PMID 39065554, 2024). "Of all 631 participants, the median nadir CD4+ T lymphocyte count was 297 cells/mm (IQR: 190–450) and 13% (n = 81) had had an opportunistic infection, mainly tuberculosis (38/81; 47%)." (PMID 39027943, 2024). "Vaccines that can trigger atypical T-cell responses in addition to regular CD4 + and CD8 + T cell responses have become the most recent frontier in the fight against tuberculosis." (PMID 38459508, 2024). "We performed single-cell RNA-sequencing analysis of CD4+ T and CD8+ T cells isolated from peripheral blood mononuclear cells of healthy individuals and patients with tuberculosis to reveal the cellular characteristics." (PMID 36916943, 2023). "An immunoassay kit with two separate stimulation pools for CD4+ and CD8+ T cells is already available for tuberculosis and HCMV, underscoring the feasibility of such an approach." (PMID 37234158, 2023). "CD4 measurement remains important for patients with CD4 <100 cells/mm3, however, who should have faster ART initiation and compulsory screening for other diseases such as Cryptococcus and Tuberculosis." (PMID 36802388, 2023). "Other studies explain the reduced CD4+T lymphocyte content and thus the reduced CD4+/CD8+ ratio by circulating soluble IL-2 (CD25) receptors in both sarcoidosis and tuberculosis." (PMID 36982159, 2023). "This prospective comparative study evaluated CD4+ and CD8+ lymphocytic subpopulations and antituberculosis antibodies in patients with diabetes and tuberculosis (TB-DM), before and after antituberculosis treatment." (PMID 37764989, 2023).